CXCL10 (C-X-C motif chemokine ligand 10)
Diseases named in the same sentence as CXCL10 in open-access papers (continued):
Sharing a sentence is not in itself a finding about the gene and the disease.
infection (continued). "Finally, among the elevated serum cytokine levels for the acute phase of infection, many were monocyte chemoattractants or secreted by monocytes and macrophages (e.g., CXCL10, CCL2, and IL‐10)." (PMID 30150281, 2018). "Similar to airway epithelial cells, human macrophages express type I and type III IFNs, IL-1α, IL-1β, IL-6, TNF-α, CXCL8, CCL2 (MCP-1), CCL3 (MIP-1α), CCL4 (MIP1-β), CXCL9, and CXCL10 following infection with seasonal H1N1 or with H5N1, 2009 H1N1 strains demonstrating increased pathogenicity." (PMID 29623073, 2018). "The rate of migration of sensory and motor Fbs was suppressed by CXCL10- or CXCL3-siRNA infection." (PMID 30686982, 2018). "In particular, CCL2, CXCL5, and CXCL10 had increased levels early after wounding and infection." (PMID 30138446, 2018). "IL-17 induces the expression of pro-inflammatory cytokines and chemokines, such as G-CSF, IL-6 and IL-8, promoting recruitment of neutrophils and granuloma formation, as well as the expression of other chemokines, including CXCL10 that recruits IFNγ producing cells to the site of infection." (PMID 29554138, 2018). "Both groups exhibited a significant increase in expression of CXCL9 and CXCL10 during the infection which could be correlated with the levels in T cell and monocytes." (PMID 30248353, 2018). "From the results of three independent experiments, we found that the inability to undergo autophagy during infection led to higher expression of many pro-inflammatory genes as compared to autophagy-competent cells, including established ISGs, such as Psmb10, Cd274, Cxcl10, Irf1 and Tap1." (PMID 29748576, 2018). "IP-10 (or C-X-C motif chemokine (CXCL)-10) is a chemokine induced by IFN-γ, which has been consistently found to be elevated in different stages of HIV infection, including acute/early infection, and it has been mostly associated with the worst-case scenarios in terms of disease progression." (PMID 29342870, 2018). "We first choose to measure the mRNA levels for iNOS, a gene that is transcribed in vivo by cardiomyocytes in response to LPS inoculation, as well as those for CCL5, CCL7 and CXCL10, three chemokines transcribed in newborn cardiomyocytes after in vitro infection with T. cruzi." (PMID 30067739, 2018). "CXCL10 (IP-10) released by infected alveolar macrophages is considered an important chemokine responsible for the directed migration of these Th1 cells to the site of infection." (PMID 30026741, 2018). "The chemokine Cxcl10 is responsible for the recruitment of CD8+ T-cells after WNV-infection." (PMID 30001706, 2018). "Changes in CXCL10 expression are well correlated with many infectious diseases, although the role of CXCL10 in viral pathogenesis and its signaling pathways is still poorly understood (as it seems to alternately promote or protect against infection in different studies)." (PMID 30150281, 2018). "The infection was associated with limited immune cytokine/chemokine response activation; the highest increase of expression, following infection, was seen in CXCL-10 (IP-10), interleukin-6, 8, 12, and CCL5 (RANTES)." (PMID 29463209, 2018). "This may indicate that HBV actively subverts CXCL10 production and the lower infection efficiency of 2D PHH cultures allows for its production by uninfected bystander cells." (PMID 29445209, 2018). "In addition, CXCL10 exhibits chemo-attractive effects on macrophages, T cells, NK cells, and dendritic cells, which promotes the host to clear infection." (PMID 28392790, 2017). "Herein, it was assessed whether treatment with CXCL10 would confer protection against infection by L. infantum in macrophages and in BALB/c mice." (PMID 28767981, 2017). "Notably, we observed upregulated mRNA expression levels of IFNα/β, IL6, TNF and several chemokines as CXCL10 or CXCL11 after USUV infection." (PMID 28873445, 2017). "Herein, it was investigated the role of CXCL10 in controlling infection by L. infantum." (PMID 28767981, 2017).
infection (continued). "Also, in vivo, it was observed that treatment with CXCL10 was able to reduce the parasite load in both liver and spleen, four weeks after infection, representing a higher decrease in the number of parasites in these organs." (PMID 28767981, 2017). "We document a sharp increase in the inflammatory response in terms of Ifng, Tnfa, Il6, Il1b, Il1r1, Cxcl9 and Cxcl10 expression already on day 6 post-infection in WT mice, and of Cd8a on day 7, which were essentially absent in ST2-/- mice on day 5 to 7 after PbA-infection." (PMID 28448579, 2017). "Interestingly, expression of CXCL-10 (IP-10) was significantly attenuated by La depletion following infection with both SeV strains, compared with scrambled controls." (PMID 29109527, 2017). "Additionally, we show that primary SVV infection induces CXCL10 expression in neurons, SGC, and infiltrating lymphocytes." (PMID 26676825, 2016). "The increased number of T cells in ganglia after primary SVV infection might reflect recruitment of T cells via expression of chemokines such as CXCL10, followed by local proliferation of T cells." (PMID 26676825, 2016). "In our analysis, we observe that a subset of these cytokines reported to be present in the serum also show transcriptional upregulations in PBMCs by 4 days post-infection (IL6, IL1B, IL1RN, CCL8, CXCL10) and by 7 days post-infection (CCL2, CCL3, CSF1, TNF, CXCL1, FAS and CXCL8)." (PMID 27595844, 2016). "Among these genes, several encode chemokines (IL8, CXCL1, CXCL10, CXCL11, CXCL9, PF4, PPBP), a family of small proteins that play important roles in the immune system through leukocyte recruitment, cell communication and cell activation during infection." (PMID 26791855, 2016). "After initial Leishmania infection of macrophages and dendritic cells, these cells produce proinflamatory cytokines and chemokines, such as TNF-α and CXCL-10, that in turn recruit new host cells (natural killer cells (NK), monocytes and neutrophils) to the infection site." (PMID 27668434, 2016). "Examination of chemokine expression at memory showed that infection resulted in sustained upregulation of transcripts encoding for a variety of different chemokines, including CCL1, CCL2, CCL5, CCL8, CXCL9 and CXCL10 compared with control flank skin from the same animals." (PMID 27160938, 2016). "In addition, the levels of CXCL1/KC and CXCL10/IP-10 in BALF from Mint3−/− mice remained lower than those from WT mice on day 8 after infection." (PMID 27883071, 2016). "As hypothesized, the levels of inflammatory mediators (IL-6, CCL2, CCL3, CXCL1, CXCL10 and IFNα as expected) were lower in the blood and the spleen of Ifnar1-/- mice compared to WT counterparts at all times post-infection, except for IFNγ." (PMID 27792766, 2016). "IP-10/CXCL-10 transcript level was previously quantified in kidneys from hamsters infected with virulent leptospires and showed an increase of the gene expression during the acute phase of infection." (PMID 27219334, 2016). "The CXCL10 rs56061981 non-GG genotype was associated with a higher rate of SVR achievement than GG genotype only in patients with HCV genotype 1 infection that had unfavorable IL28B rs12979860." (PMID 26339796, 2015). "Having shown that extracellular histones are generated during infection, we next investigated whether this leads to an induction of CXCL10 in the air pouch." (PMID 26646682, 2015). "In the i.n. model, infection by vΔ169 caused enhanced production of several cytokines (IL-2, IL-6 and TNF-α) and chemokines (CCL11, CXCL9 and CXCL10) within 1 day p.i. and subsequent greater recruitment of macrophages and CD4+ and CD8+ T cells and increased lung weight." (PMID 26334635, 2015). "However, very shortly after infection (3 days after infection), during the incubation period, CXCL10 and CXCL11 mRNA levels were found to be higher in the PBMC of the monkeys that subsequently survived the acute infection than in the PBMC of monkeys that died." (PMID 24421914, 2014).
infection (continued). "The contradictory findings of CXCL10's role in either protecting or promoting infection may depend on the host immune status and genetic background." (PMID 24701034, 2014). "Neutrophils that are primarily recruited by CXCL8 can exert antiviral immunity amongst others by the release of inflammatory cytokines (e.g., IL-12, TNFα) and chemokines (e.g., CCL2, CXCL8, CXCL9, CXCL10) that leads to further recruitment of immune cells to the site of infection." (PMID 24646914, 2014). "Furthermore, the infection of mice with CPn via the intranasal route also induced CXCL10 in the airways and enhanced inflammation." (PMID 25253920, 2014). "Furthermore, the gene expression of the cytokines Cxcl9, Cxcl10, Cxcl11 and Ccl20 was increased early after infection." (PMID 25137043, 2014). "Conversely, patients who survived could promote type-1 IFN response, control viral replication, and down-regulate this response, exhibiting low levels of CXCL10 when recovering from infection." (PMID 24551142, 2014). "Similarly, the median CXCL10 concentration in the serum increased from 142 pg/mL to 385 pg/mL, 443 pg/mL, and 338 pg/mL at 2, 4, and 6 weeks post-infection, respectively (p<.01, <.001, and <.05, respectively, compared to non-infected controls)." (PMID 23940724, 2013). "The observed increases in airway T cell number in immunized and infected mice might in part be explained by the enhanced levels of the T cell recruiting chemokine CXCL10 measured in BAL 24 hrs after infection." (PMID 24086140, 2013). "CCL2 and CXCL10 are chemokines that are low molecular weight molecules and play a pivotal role in the orchestration of an effective antiviral immune response, partly by attracting leukocytes to the site of inflammation or infection." (PMID 23637938, 2013). "Of note, however, CXCL10 production is also induced directly by infection of human AMø by rhinovirus, of murine AMø by RSV and of human MDMø by influenza or HIV, making this cytokine a suitable endpoint to test the functional importance of the observed TLR3 downregulation." (PMID 23497334, 2013). "NF-kB binding sites are present in the CXCL10 gene promoter so this chemokine production may be related to the NF-kB activation observed after infection." (PMID 24367259, 2013). "Similarly, other genes associated with the mammary gland response to infection are expressed at higher levels in SA24T0, e.g. S100A8, S100A12, CXCL10, interleukin (IL) 1B and lactotransferrin (LTF)." (PMID 23324411, 2013). "However, levels of mRNAs for some chemokines, including CCL4 and CXCL10, were up-regulated compared to mock-infected cells at this time point following infection." (PMID 23265239, 2013). "The activation of astrocytes and macrophages are early events in stage 2 infection, suggesting that CXCL10 may represent an early indicator of CNS involvement in HAT." (PMID 23369533, 2013). "UV-inactivated HSV-1 elicited a greater CCL3 and CXCL10 response compared to infection with replication competent virus; therefore, the present data support previous findings suggesting that viral replication products inhibit IFN and chemokine expression in human macrophages as well as other cells." (PMID 23062757, 2012). "Finally, secretion of CXCL10 by NiV-infected HUVECs was demonstrated by ELISA up to 72 h of infection, confirming the NiV infection induces the expression of CXCL10 at the protein level as well." (PMID 22393386, 2012). "In addition, neutralization of CXCL10 decreased leukocyte migration to areas of infection in measles virus-infected brain tissue." (PMID 22393386, 2012). "Altogether, these results indicated that NiV-infection activates cellular pathways leading to an increase of CXCL10 expression that may play a role in the pathogenesis of this highly lethal emergent infection." (PMID 22393386, 2012).
infection (continued). "The levels of CXCL1, CXCL10, CCL1, CCL3, IFN-γ, TNF-α and IL-6 were significantly increased in the lungs of RSV-infected IL-10-deficient mice compared to control mice on day 8 post infection." (PMID 22393401, 2012). "A pro-inflammatory response may be required in order to more effectively clear infection, however prolonged NF-κB activation, and subsequent production of IL-8, RANTES and CXCL10, has been implicated in animal models of IBD." (PMID 22039501, 2011). "In addition, elevated levels of CXCL10 have been reported in plasma and infection foci in individuals infected with MTB." (PMID 21904626, 2011). "In the ferret model with 27% mortality based on the >20% weight loss following infection with A/California/07/2009 pandemic influenza virus, sequential lung sampling documented decreased gene expression of CCL2, CXCL10, TNFA and IL1B on day 7 when animals show highest weight loss." (PMID 20957032, 2010). "Although we focused here on the role of IFN-γ in stimulating CD14+ monocytes/macrophages to secrete CXCL9 and CXCL10, other factors and cell types may be involved in the actual infection." (PMID 20828409, 2010). "CXCL9 and CXCL10 are each induced to relatively high levels within the lungs following spore challenge suggesting that antimicrobial activity may act early in infection against the spore form of the organism." (PMID 21124994, 2010). "The CXCR3 ligands CXCL9, CXCL10, and CXCL11 are potent chemotactic factors for activated T cells, which are highly susceptible to infection in vivo, and these IFN-γ-inducible chemokines are consistently increased in expression in multiple tissues following SIV infection." (PMID 19149556, 2009). "Most importantly, chemokine genes e.g., Cxcl9, Cxcl10, Cxcl11, Cxcl13, Ccl3, Ccl5 and Ccl12 that exert a chemotactic signal for the immune cell migration to the site of the injury were upregulated at 72 and 96 hr post infection." (PMID 18558011, 2008). "CXCL10 mRNA was detected as early as day 1 after infection and was elevated by more than 400-fold." (PMID 23675028, 2007). "However, given this biology, CXCL10 may have limited sensitivity for early stage, low viral load infections." (PMID 40543450, 2025). "Similarly, CXCL-10, a chemokine, plays an important role in attracting immune cells to sites of infection and immune activation and may thereby contribute to a cascade of cytokine production in Dengue infection." (PMID 41227147, 2025). "Similarly, CXCL10 is vital for protective immune responses, as it facilitates recruitment and activation of NK cells while also attracting activated T cells, NK cells, and dendritic cells to infection sites." (PMID 40298680, 2025). "However, Cxcl9 and Cxcl10 could play a more important role during a secondary infection that involves the adaptive immune response." (PMID 38352492, 2024). "Moreover, CCL8 may have a potential interaction with CXCL10, which has been identified as an important gene of early infection in the influenza A pathway." (PMID 38960408, 2024). "The correlation between non-classical monocytes, symptom severity, and the production of interferons, CXCL10 and IL-8 after iSARS-CoV-2 stimulation indicates important differences in anti-viral innate immune response between PCR+ children and adults early after infection." (PMID 39624095, 2024). "However, in addition to IL-12, GRA24 upregulates several other proinflammatory cytokines and chemokines, including IL-6, TNF, MCP-1, CCL5, CXCL1, and CXCL10 that could contribute to the lethal outcome of infection." (PMID 39440975, 2024). "Furthermore, SARS-CoV-2 D614G[Omicron spike] infection resulted in a significantly increased expression of ISGs Mx1, Oas1, and Viperin as well as Cxcl10, while pro-inflammatory mediators Cxcl1, Ccl2, and Il6 were not significantly altered in any group compared to the uninfected mice." (PMID 38742107, 2024).
infection (continued). "Notably, infection by the Delta variant induced significantly higher levels of chemokine mRNAs such as CXCL9, CXCL10, CXCL11, and CCL2 than infection by the wild type and there was negligeable upregulation of cytokine and chemokine mRNA levels in mice infected with Omicron at 3 dpi." (PMID 38257760, 2023). "Here, we demonstrated that Att-S74-T3Bo infection induces alterations in innate immune myeloid and lymphoid cells in peripheral blood, eliciting significant levels of the pro-inflammatory cytokines TNFα, CXCL10, and IFNγ in sera as early as 3 days post-infection." (PMID 36466866, 2022). "Once recruited in the site of infection, neutrophils release different proinflammatory mediators, including cytokines (interferon-α, interferon-β, tumor necrosis factor, and interleukins 1β, 6, and 10) and chemokine (e.g., CXCL10) that participate in COVID-19 pathogenesis." (PMID 35336077, 2022). "Furthermore, we also determined mRNA transcripts for one ISG that is involved in attracting T cells to the site of the infection (CXCL10) to evaluate whether there was an upregulation of the transcripts without there being direct antiviral effects." (PMID 36423126, 2022). "Moreover, Cxcl10 expression was significantly increased in mice infected with ΔospC1/C3 Shigella, compared with WT Shigella, despite the lower bacterial titers observed in the ΔospC1/C3 infection." (PMID 35568036, 2022). "Additionally, CXCL10 is activated early in infection in WT cells but less so in KD/KO cells." (PMID 35085371, 2022). "Moreover, the levels of infection-induced CXCL10 and CXCL11 were reduced." (PMID 35479095, 2022). "Inflammatory cells infiltrate the sites of infection at an early stage of the infection with SARS-CoV2 and cause a stormy release of pro-inflammatory cytokines like IL-6, IL-17A, TNFα, IFNγ, IL-1α/β, and chemokines like CC-chemokine ligand 2 (CCL2) as well as CXC-chemokine ligand 10 (CXCL10)." (PMID 33643316, 2021). "Additionally, infection of PBMCs in vitro has been shown to increase CXCL10 expression." (PMID 33668216, 2021). "Transplantation of healthy human islets in these mice reversed hyperglycemia, but this effect was abrogated upon infection of these mice with Coxsackievirus B. Signatures of viral RNA and increased levels of interferon-stimulated genes, CXCL10 and CCL5, could be observed in the transplanted islets." (PMID 33469446, 2020). "Indeed, joint inflammation was alleviated in Cxcl10−/− mice, and this was accompanied by a significant reduction in macrophages, which constituted the largest immune cell population in joints following infection." (PMID 33147869, 2020). "Therefore, the dysregulation of CXCL10 expression in the lung tissue and systemic circulation during infection could play an essential role in the pathogenesis of pathogenic coronaviruses." (PMID 32365944, 2020). "Furthermore, ssON treatment of RSV-infected mice increased the RSV-induced expression of Cxcl10 and Ccl2, which are both reported to recruit immune cells, such as monocytes, dendritic cells and T cells, to sites of infection or inflammation, thereby aiding in viral clearance." (PMID 33363532, 2020). "Infection with RV1b resulted in increased rhinovirus load measured via qPCR compared to UV-inactivated RV1b (31.3 ± 29.8 copy #/ng RNA vs. 2.37 × 107 ± 1.46 × 107 copy #/ng RNA; p < 0.05), increased typical pro-inflammatory viral cytokines CXCL10 and CCL5, and type I and III interferon responses." (PMID 32328066, 2020). "While we did detect small increases in the levels of CXCL10 and IL-6 with abortive infection of VA1 in SW-1088 cells, it is unclear whether these increases are biologically significant, and further characterization may reveal host responses that are significantly induced by abortive infection." (PMID 31289185, 2019).